Y_RNA (Y RNA )
Gene: Miscellaneous RNA gene on chromosome 16 (69,191,123 to 69,191,223, forward strand). Ensembl gene ENSG00000200164.
Homologues: Orthologues: chimpanzee Y_RNA (100% identical), macaque Y_RNA (98% identical). Paralogues in human: RNY3 (93% identical), Y_RNA (93% identical), Y_RNA (92% identical), RNY3P1 (91% identical), Y_RNA (91% identical), RNY3P14 (90% identical), Y_RNA (90% identical), Y_RNA (89% identical), RNY3P11 (88% identical), Y_RNA (88% identical), Y_RNA (87% identical), RNY3P16 (86% identical), and 95 more.